IL3 (interleukin 3)
Diseases named in the same sentence as IL3 in open-access papers (continued):
Sharing a sentence is not in itself a finding about the gene and the disease.
Obesity (8 papers, 2010 to 2024). Accumulation of substantial excess body fat. "Obesity is said to cause chronic inflammation and inhibition of viral killing by delaying IL-1 and IL-3 reactions." (PMID 39659767, 2024). "The hyperplasia andhypertrophy of adipose tissues caused by obesity are often driven by theexcessive release of pro-inflammatory cytokines from these tissues, known asadipokines, including TNF-α, IL-6, and interleukin-3 (IL-3)." (PMID 39742220, 2024). "Although IL-3 has been reported to be upregulated in obesity, few studies have reported differences in IL-3 levels in overweight and normal-weight patients with MDD." (PMID 36387880, 2022). "In obesity, the secretion of multiple cytokines including IL-3, IL-7, IL-8, TNFα and chemokines including monocyte chemotactic protein-1 (MCP-1, also called Chemokine C-C motif ligand 2 (CCL2)), are upregulated." (PMID 33105727, 2020). "These clusters included previously reported biomarkers for obesity-related disease and potential new biomarkers such as IL-3 and IL-13." (PMID 21203453, 2010). "It is well known that a decrease of NFATC2 expression is associated with a reduction of the expression of cytokines in T cells, in particular IL-2, IL-3, IL-4 and TNF-alpha; the latter, in particular, is a pro-inflammatory cytokine associated with obesity and insulin resistance." (PMID 35159548, 2022).
ovarian carcinoma (8 papers, 1993 to 2023). A malignant neoplasm originating from the surface ovarian epithelium. "The proangiogenic cytokine Interleukin-3 (IL-3) is released by inflammatory cells in breast and ovarian cancer tissue microenvironments and also acts as an autocrine factor for human breast and kidney tumor-derived endothelial cells (TECs)." (PMID 29238040, 2018). "An increase in IL-3 and IL-10 expressions, insulin-like growth factor binding proteins (IGFBP) IGFBP-1, IGFBP-2 and IGFBP-3 levels were detected in both ovarian cancer cell lines with leptin administration." (PMID 37155466, 2023). "After 21 days of induction with SFTG36 (SCF, FLt-3L, TPO, GM-CSF, IL-3 and IL-6), IS721 (IGF-1, SIS3, IL-7 and IL-21) and IL-15/Hsp70 media, NK cells phenotypes were studied and their cytotoxicity against K562 human erythroleukemia cells and SKOV3 ovarian carcinoma cells was analyzed." (PMID 34098947, 2021).
allergic asthma (7 papers, 2018 to 2023). A asthma with a basis in a pathological type I hypersensitivity reaction. "To start investigating the function of IL-3 in allergic asthma, we analyzed the IL-3 secretion in the NPF of the cohort of our study PreDicta including 21 healthy controls and 24 asthmatic preschool children." (PMID 35281014, 2022). "While anti-IL-5 treatment has been widely approved for treating eosinophilic asthma, attenuation of broad-range inflammatory and physiological changes after allergen challenge suggests that blocking CCR3, IL-3, and GM-CSF are also important targets for the management of allergic asthma." (PMID 33917396, 2021). "Also, TSLP activation of basophils in allergic asthma patients is IL-3 dependent." (PMID 31941161, 2020). "IL-5, IL-3, and GM-CSF are present in bronchoalveolar lavage (BAL) fluid from subjects with mild allergic asthma and are increased after segmental lung antigen challenge." (PMID 30048528, 2018).
atherosclerosis (7 papers, 2017 to 2025). A disease characterized by the build-up of fatty material and calcium deposition in the arterial wall resulting in partial or complete occlusion of the arterial lumen. "On the other hand, IL-12 (p70), fractalkine, IL-6, and IL-3 are associated with atherosclerosis with stenosis below 70%, where IL-6 can promote endothelial dysfunction and fractalkine can contribute to the early stages of plaque development and mild stenosis." (PMID 37629267, 2023). "CT-1 deficiency in advanced atherosclerosis mediated regulation of paracrine factors, such as interleukin (IL)-3, IL-6, IL-9, IL-15, IL-27, CXCL5, MCP-3, MIP-1α and MIP-1β." (PMID 32238841, 2020). "Interleukin-3 (IL-3), tumor necrosis factor-α (TNF-α), and interferon-γ have been identified as key factors that activate macrophages, endothelial cells, and vascular smooth muscle cells, thereby exacerbating local inflammation and promoting the progression of atherosclerosis." (PMID 41383228, 2025).
depression (7 papers, 2020 to 2025). "Additionally, analysis of serum IL-3 and lipocalin-2 levels provided significant diagnostic value for MDD patients and can be an effective indicator of probable depression development." (PMID 37957650, 2023). "Further interventional studies are recommended for a better understanding of the role of IL-3 and lipocalin-2 in the pathophysiology of depression." (PMID 37957650, 2023). "Recently, a meta-analysis including 107 studies regrouping 5,166 patients with depression and 5,083 controls indicated that levels of IL-3 were significantly higher in patients with depression." (PMID 36387880, 2022). "In a meta-analysis studying inflammatory markers in depression (collecting 5166 patients with depression and 5083 healthy controls), the researchers found that IL-6, TNF-α, IL-12, IL-3, IL-18, and sIL-2R were elevated in depression group." (PMID 36408212, 2022). "Moreover, a meta-analysis demonstrated elevated plasma levels of interleukin-3 (IL-3), interleukin-12 (IL-12), and interleukin-18 (IL-18) in patients with depression." (PMID 41226404, 2025). "Therefore, Increased IL-3 levels can contribute to the symptoms of neuropsychiatric illnesses like depression." (PMID 37957650, 2023). "A meta-analysis of cytokine alterations in the blood, based on 107 studies comprising a total of 5,166 patients with depression compared to 5,083 healthy controls, found levels of IL-3, IL-6, IL-12, IL-18 and TNF-ɑ to be higher in blood from the patients with depression." (PMID 37016363, 2023). "Therefore, altered serum levels of IL-3 have been observed in patients with mood disorders and lipocalin-2 in patients with late-life depression." (PMID 37957650, 2023). "The Association between IL-3 and depression has not been investigated in Bangladeshi population yet but we found significantly higher IL-3 levels in the serum of MDD patients than HCs (p = 0.002) in our study." (PMID 37957650, 2023). "The present study aimed to evaluate serum IL-3 and lipocalin-2 in MDD patients and healthy controls (HCs) to understand their role in the pathophysiology and development of depression." (PMID 37957650, 2023). "Our meta-analysis finds evidence that mean-scaled variability, measured as CVR, is reduced in patients with depression for CRP, IL-12 and sIL-2R, while it is unchanged for IL-3, IL-6, IL-18 and TNF α." (PMID 32113908, 2020). "We found increases in the mean levels of CRP, IL-3, IL-6, IL-12, IL-18, sIL-2R and TNF α in patients with depression." (PMID 32113908, 2020). "The finding of altered peripheral levels of IL-3 and lipocalin-2 in MDD patients may indicate a strong relationship between the pathophysiology of depression and these biomarkers." (PMID 37957650, 2023). "In the same sample, we also find that blood levels of CRP, IL-3, IL-6, IL-12, IL-18, sIL-2R and TNF α are significantly elevated in patients with depression with medium-large effect sizes (range 0.54–1.97), and that these findings are robust to a range of potential confounds and moderators." (PMID 32113908, 2020).
leukocytosis (7 papers, 2013 to 2024). "HDL-C suppresses myeloid proliferation and leukocytosis by decreasing granulocyte-monocyte progenitors and proliferation of interleukin-3 in bone marrow cells." (PMID 33572660, 2021). "Despite stimulating bone marrow to sustain leukocytosis, IL-3, GM-CSF, and G-CSF have been shown to stimulate the growth of clonogenic cells of some nonhematopoietic malignant cell lines in vitro." (PMID 25223869, 2014). "WBC counts are elevated in ATC in part because some ATC cells produce several growth factors and cytokines, such as colony-stimulating factor (CSF), interleukin-1α (IL-1α), IL-3, and IL-6, which lead to leukocytosis." (PMID 24224029, 2013). "By reducing the proliferation rates of interleukin-3 and granulocyte-monocyte progenitors in bone marrow cells, HDL-C inhibits leukocytosis and myeloid proliferation." (PMID 38540127, 2024). "By reducing the growth of interleukin-3 and granulocyte-monocyte progenitors in bone marrow cells, HDL-C inhibits myeloid proliferation and leukocytosis." (PMID 38540127, 2024).
lung carcinoma (7 papers, 2015 to 2024). "For example, T-cell lymphoma, classic Hodgkin lymphoma, SM, AML, MPN, and certain solid tumors (e.g., lung cancer, renal cell carcinoma, etc.)can abnormally release IL-2, IL-3, IL-5 or GM-CSF." (PMID 38611061, 2024). "In accordance with its established physiological roles, IL-3 was found to increase tumor immunogenicity in mouse models of lung cancer and fibrosarcoma by promoting development of tumor reactive cytotoxic T cells and by promoting infiltration and activation of anti-tumorigenic macrophages." (PMID 26361584, 2015). "Notably, among them (IL1-β, IL-3, MCP-1, TNF-α), the EGF, the most acknowledged target for lung cancer therapy, emerges." (PMID 36733673, 2023).
malaria (7 papers, 2013 to 2025). Malaria is a serious and sometimes fatal disease caused by a parasite that commonly infects a certain type of mosquito which feeds on humans. "The IL‐3 single nucleotide polymorphisms rs40401TT and rs40401CT were observed to provide protection against malaria attacks." (PMID 39240033, 2024). "This is also consistent with linkage analyses in mice and genetic studies in humans showing an association of IL3, IL4, IL13, IRF1, and ARHGAP26 with parasitaemia, mild malaria or severe malaria." (PMID 24884991, 2014). "These sustained production of GM‐CSF and IL‐3 from B1b B cell plasmablasts underscores the phenotypic diversity and functional importance of these cells for mounting an effective immune response against malaria." (PMID 41171200, 2025). "Activated T cells and B cells are a primary source of IL-3 in humans; and therefore, it remains possible that repeated malaria could condition antigen-specific adaptive immune cells to produce less IL-3 upon activation, leading to less potent activation/priming of innate immune cell responses." (PMID 39161730, 2024). "On the other hand, children with severe malarial anemia had lower IL‐3 and TGF‐β levels than those with uncomplicated malaria in the current study, and this is similar to previous findings." (PMID 39240033, 2024). "Malaria presents with enhanced release of TNF‐α, IFN‐ɣ, IL‐1β, IL‐6, GM‐CSF, and IL‐10, but downregulates IL‐3 and TGF‐β in Ghanaian children." (PMID 39240033, 2024). "Severe malarial anemic children had elevated TNF‐α (p < .001), IFN‐ɣ (p < .001), IL‐1β (p < .001), IL‐6 (p < .001), GM‐CSF (p < .001), and IL‐10 (p < .001), but lower IL‐3 (p < .001) and TGF‐β (p < .001) than those with uncomplicated malaria." (PMID 39240033, 2024). "In contrast, plasma levels of IL‐3 and TGF‐β were relatively lower among participants with severe malarial anemia than those in the uncomplicated malaria group." (PMID 39240033, 2024). "Although plasma levels of IL‐3 and TGF‐β were similar between children with malaria and the uninfected group, the levels of the cytokines were lower in participants with hyperparasitemia in the present study, and this observation is similar to earlier findings." (PMID 39240033, 2024). "In addition, malaria status predicted TNF‐α, IFN‐ɣ, IL‐1β, IL‐6, GM‐CSF and IL‐10 levels, whiles anemia severity predicted only IL‐3, IL‐10 and TGF‐β levels." (PMID 39240033, 2024). "Moderate associations were found between some immune response genes (ie, IL3 and IL13) and parasite rates, but these could not be reproduced using the alternative measures of malaria propensity." (PMID 28541483, 2017).
myeloid leukemia (7 papers, 2001 to 2021). A clonal proliferation of myeloid cells and their precursors in the bone marrow, peripheral blood, and spleen. "However, ectopic expression of Trib2 alone in 32D cells (an IL-3-dependent myeloid leukemia cell line), or in TF-1 cells, induces a strong apoptotic response." (PMID 30266989, 2019). "Consistent with this, a recent study has revealed that all three Pim kinases, including Pim-3, activated the indistinguishable downstream signaling cascades, protected FL5.12 cells from IL-3 withdrawal, and cooperated with Myc to induce myeloid leukemia in mice." (PMID 29507660, 2018).
Stroke (7 papers, 2009 to 2025). Sudden impairment of blood flow to a part of the brain due to occlusion or rupture of an artery to the brain. "IL3 is strongly associated with brain volume variation and plays pivotal roles in the expansion and maintenance of the neural progenitor pool and the number of surviving neurons; our work has previously identified IL3 increased in the spleen with our aged rat model of stroke." (PMID 36825211, 2022). "In this study, the ameliorating effect of a cytokine mixture consisting of granulocyte-macrophage colony-stimulating factor (GM-CSF) and interleukin (IL)-3 was evaluated on ischemic brain injury using a rat stroke model prepared by transient middle cerebral artery occlusion (tMCAO)." (PMID 35968363, 2022). "Although the higher levels of these cytokines might be explained by a higher number of CXCL9-producing monocytes and IL-3-producing T cells in the spleen, upregulation of chemotactic cytokines may provide a beneficial role after stroke by drawing inflammatory cells away from the brain." (PMID 33376583, 2020). "The levels of salivary growth factors (IL-3, PDGF-BB) were also lower in the saliva of stroke patients." (PMID 40221607, 2025). "Salivary basic FGF, HGF, IL-3 and LIF could serve as potential biomarkers for stroke." (PMID 40221607, 2025).
Autoimmunity (6 papers, 2012 to 2025). The occurrence of an immune reaction against the organism's own cells or tissues. "Hartl’s research indicates that reduced DNase IL3 activity in Lupus Nephritis (LN) patients is linked to neutralizing anti-DNase IL3 antibodies, which contribute to increased cfDNA accumulation and anti-DNA autoimmunity in SLE." (PMID 40008123, 2025). "In autoimmunity, IL-3 and other cytokines are important for the proliferation of regulatory T cells (Tregs)." (PMID 27835969, 2016). "Here, we show that GM-CSF and IL-3, hematopoietic cytokines that play a central role in regulating myeloid cell expansion and effector response in several in vivo models of inflammation and autoimmunity, modulate human CD14+ monocyte response in short- and long-term models of trained immunity." (PMID 28138327, 2016).
colon carcinoma (6 papers, 2015 to 2022). "In the meantime, KEGG pathway enrichment indicated that the major mechanisms of THCQF inhibited colon cancer were associated with the interleukin (IL)-4 and IL-3 signaling pathways." (PMID 35479514, 2022). "GO and KEGG enrichment analyses indicated that the activity against colon cancer of THCQF was associated with the interleukin (IL)-4 and IL-3 signaling pathways." (PMID 35479514, 2022). "After controlling for multiple comparisons, authors found that single nucleotide polymorphisms (SNPs) from four genes, IL3, IL6R, IL8, IL15, were associated with increased colon cancer risk." (PMID 34753514, 2021). "To further analyze the functional role of mast cells in colon cancer development in vitro, we produced bone marrow-derived mast cells from mouse bone marrow cells co-cultured with IL-3 and SCF." (PMID 26978404, 2016). "We confirmed the Bax/Bak requirement for HSV-1-induced apoptosis in other mouse cells, IL-3 (factor)-dependent monocytes (FDMs) as well as in human HCT116 colon carcinoma cells." (PMID 26030884, 2015). "Indeed, when Puma was genetically deleted or downregulated by shRNA, mouse embryonic fibroblasts and IL-3-dependent monocytes as well as human colon carcinoma cells were as resistant to virus-induced apoptosis as their Bax/Bak double deficient counterparts (Bax/Bak-/-)." (PMID 26030884, 2015).
helminth infection (6 papers, 2015 to 2023). "The previous research of defense mechanisms against helminths infections is typically associated with a type 2 immune response characterized by the expression of the cytokines IL-3, IL-4, IL-5, IL-9, IL- 10, and IL-13." (PMID 32243446, 2020). "Another group showed that IL-3 plays a role in basophil recruitment to draining LNs using helminth infection model with mice deficient in IL-3 or IL-3Rβ." (PMID 26284076, 2015). "The accumulation of basophils in the lymph nodes after helminth infection depends on IL-3 from CD4+ T cells, while IL-3 supplied by skin-resident CD4+ memory T cells is essential for their recruitment to the skin in the setting of tick bite." (PMID 36618424, 2022). "The immune response during helminth infection is supported by T helper 2 (Th2) lymphocytes, with release of cytokines, such as interleukin 3 (IL3), IL4, IL5, IL9 and IL13, eosinophilic granulocytes, mast cells and activated macrophages." (PMID 34944226, 2021).
osteoarthritis (6 papers, 2017 to 2025). A noninflammatory degenerative joint disease occurring chiefly in older persons, characterized by degeneration of the articular cartilage, hypertrophy of bone at the margins and changes in the synovial membrane. "It was reported that avocado and soybean unsaponifiables can restrain osteoarthritis through inhibition of proinflammatory cytokines such as IL-1β, IL-3, IL-6, IL-8, IL-13, and TGF-β; also, they can modulate oxidative damages by repression of ROS production." (PMID 34258301, 2021). "Previously, reports have shown that IL3 prevents bone and cartilage damage in animal models of human rheumatoid arthritis and osteoarthritis." (PMID 30956670, 2019). "Previously, we have reported that interleukin-3 (IL-3) prevents bone and cartilage damage in animal models of rheumatoid arthritis and osteoarthritis." (PMID 28705238, 2017). "Previously, we have reported that IL-3 prevents bone and cartilage damage in animal models of human rheumatoid arthritis and osteoarthritis." (PMID 28705238, 2017). "Interestingly, females with osteoarthritis show higher levels of IFN-γ, IL-3, IL-8, IL-18, and TNF-β, and other factors that stimulate macrophages compared to osteoarthritis men." (PMID 39439003, 2024). "However, IL3, a specific ligand of IL3RA, plays a chondroprotective role in osteoarthritis (OA), a degenerative disease of joints." (PMID 39456698, 2024). "However, our current study reveals an up-regulation of ACAT1 expression in the synovium of patients with osteoarthritis, and a negative correlation with the levels of TGFB2 and IL-3." (PMID 40164659, 2025).
acute lymphoblastic leukemia (5 papers, 2015 to 2025). Leukemia with an acute onset, characterized by the presence of lymphoblasts in the bone marrow and the peripheral blood. "According to the fifth edition of the World Health Organization Classification of Hematolymphoid Tumors, the IGH::IL3 fusion defines a distinct molecular subtype of B‐cell precursor acute lymphoblastic leukemia (BCP‐ALL)." (PMID 40981401, 2025).
anemia (5 papers, 2014 to 2025). A reduction in the number of red blood cells, the amount of hemoglobin, and/or the volume of packed red blood cells. "Another approach to improving the condition of anemia in this model is expressing cytokines erythropoietin and IL-3 via knock-in or hydrodynamic injection of DNA plasmids as previously reported for increased reconstitution and development of human erythrocytes." (PMID 37868989, 2023). "Moreover, IL6 is capable of correcting anemia in combination with IL3, making rapid activation of platelets by thrombin and platelet activating factor, and exhibiting a procoagulant effect on ameliorating bleeding propensity." (PMID 36297316, 2022). "In summary, CIP treatment 1) significantly improved survival after CI; 2) partially ameliorated CI-induced severe anemia; 3) increased BMP4 production by F4/80+ macrophages in spleen; and 4) elevated IL-3 concentrations in serum of CI mice." (PMID 24587369, 2014).